PIAS1 (protein inhibitor of activated STAT 1)
Diseases named in the same sentence as PIAS1 in open-access papers (continued):
Sharing a sentence is not in itself a finding about the gene and the disease.
atherosclerosis (3 papers, 2014 to 2025). A disease characterized by the build-up of fatty material and calcium deposition in the arterial wall resulting in partial or complete occlusion of the arterial lumen. "Circ‐PIAS1‐5 is identified as a potential diagnostic biomarker of HHcy‐associated atherosclerosis in male “apolipoprotein E knockout (ApoE−/−)” mice." (PMID 40089857, 2025). "Importantly, downregulation of circ‐PIAS1‐5 was implicated as an independent prognostic marker for patients with atherosclerosis complicated by HHcy." (PMID 40089857, 2025). "Collectively, these results suggest that circ‐PIAS1‐5 might be a potential diagnostic marker for patients with atherosclerosis concomitant with HHcy." (PMID 40089857, 2025). "In the present study, we identified a novel lipid metabolism‐associated circRNA, circ‐PIAS1‐5, whose expression pattern, potential diagnostic value, and prognostic significance were assessed in disorders of lipid metabolism in foam cells from patients with atherosclerosis." (PMID 40089857, 2025). "We identified a circRNA, circ‐PIAS1‐5, that was revealed to inhibit lipid deposition in foam cells in Hcy‐induced atherosclerosis." (PMID 40089857, 2025). "The circ‐PIAS1‐5 expression level was decreased and had satisfactory sensitivity and specificity in patients with atherosclerosis complicated by HHcy." (PMID 40089857, 2025). "A model is schematically represented for the major molecular mechanisms by which homocysteine (Hcy) accelerates the nuclear export of circ‐PIAS1‐5, which regulates atherosclerosis by acting as a competing endogenous RNA for miR‐219a‐2‐3p." (PMID 40089857, 2025). "More importantly, Hcy accelerates the nuclear export of circ‐PIAS1‐5, which regulates atherosclerosis, by acting as a competing endogenous RNA for miR‐219a‐2‐3p." (PMID 40089857, 2025). "Taken together, these results highlight the role of circ‐PIAS1‐5 in the Hcy‐mediated pathogenesis of atherosclerosis and suggest its potential application as a prognostic biomarker of atherosclerosis induced by HHcy." (PMID 40089857, 2025). "Activated PIAS1 gene was identified to repress the transcription of inflammatory genes, repression of PIAS1 related pathways have some effects for the treatment of inflammatory disorders such as RA and atherosclerosis." (PMID 24551036, 2014). "The existence and relevant function of circ‐PIAS1‐5 in Hcy‐induced atherosclerosis were determined." (PMID 40089857, 2025). "In this study, it is determined that homocysteine (Hcy) downregulates the expression of circ‐PIAS1‐5 by global circRNA expression profiling and that circ‐PIAS1‐5 inhibits Hcy‐mediated lipid accumulation in foam cells and the pathogenesis of atherosclerosis by acting as a sponge for miR‐219a‐2‐3p." (PMID 40089857, 2025). "Taken together, these results demonstrated that circ‐PIAS1‐5 could act as an miR‐219a‐2‐3p sponge in atherosclerosis induced by Hcy." (PMID 40089857, 2025). "Importantly, cytoplasmic expression of circ‐PIAS1‐5 alleviates miR‐219a‐2‐3p expression, causing downregulation of TEAD1 in foam cells, which consequently regulates the progression of atherosclerosis induced by Hcy." (PMID 40089857, 2025). "Thus, circ‐PIAS1‐5 might serve as a potential biomarker of atherosclerosis induced by Hcy, and it might be used in the early diagnosis, development, and prognosis of atherosclerosis." (PMID 40089857, 2025). "However, the mechanism of circ‐PIAS1‐5 in Hcy‐induced atherosclerosis is poorly understood." (PMID 40089857, 2025). "Taken together, these results demonstrated that circ‐PIAS1‐5 activates the AMP‐activated protein kinase pathway by regulating TEAD1 and contributes to atherosclerosis in ApoE−/− mice." (PMID 40089857, 2025).
glioblastoma multiforme (3 papers, 2014 to 2025). "As can be seen from the figure, UBE2I, UBA2, PIAS3, and SENP1 were upregulated in glioblastoma, whereas PIAS1, RANBP2, SENP5, and SENP2 were downregulated in glioblastoma." (PMID 33898460, 2021). "PIAS1, RANBP2, SENP5, and SENP2 were downregulated in glioblastoma." (PMID 33898460, 2021). "Moreover, UBE2I, UBA2, PIAS3, and SENP1 were highly expressed in glioblastoma, whereas PIAS1, RANBP2, SENP5, and SENP2 were downregulated in glioblastoma." (PMID 33898460, 2021).
Huntington disease (3 papers, 2024 to 2025). Huntington disease (HD) is a rare neurodegenerative disorder of the central nervous system characterized by unwanted choreatic movements, behavioral and psychiatric disturbances and dementia. "Regarding PIAS1, a protective role against Huntington’s Disease and cerebral infarction has been described through the reduction of associated inflammation and apoptosis, and PIAS genes have been proposed as disease markers in bipolar disorder." (PMID 39727940, 2024). "The upregulated PIAS1 (EXC-M5), a known modulator of striatal transcription and DNA damage repair during SUMOylation, comprises critical parts of diverse cellular processes associated in neurodegenerative diseases like Huntington's disease, Parkinson's disease, and AD." (PMID 38913039, 2024). "SiRNA-mediated knockdown of the E3 SUMO ligase protein inhibitor of activated STAT1 (Pias1), which can SUMO modify mGLUR7, reduced this Huntington’s disease phenotype." (PMID 39391934, 2025).
non-small cell lung carcinoma (3 papers, 2014 to 2022). A group of at least three distinct histological types of lung cancer, including non-small cell squamous cell carcinoma, adenocarcinoma, and large cell carcinoma. "PIAS1 is overexpressed in non-small-cell lung cancer (NSCLC) cells and other cancers." (PMID 35887358, 2022). "Co-amplification PIAS1 and FAK is reported in a subset of non-small-cell lung cancers (NSCLCs)." (PMID 34503213, 2021). "Furthermore, the amplification of PIAS1 and/or focal adhesion kinase (FAK) occurs in 8% of non-small-cell lung cancer (NSCLC) cell lines and in a small subset of patient-derived primary NSCLCs and potentially drives lung carcinogenesis." (PMID 34503213, 2021).
allergic asthma (2 papers, 2016 to 2023). A asthma with a basis in a pathological type I hypersensitivity reaction. "Thus, high expression of PIAS1 in bronchial epithelia of the patients and mouse model with allergic asthma promoted the SUMOylation and activation of ROCK2 and thereby induced the airway goblet cell metaplasia." (PMID 37393345, 2023). "Beside novel information on the cell type specific conditions leading to allergic asthma, our data may provide the basis for three novel therapeutic and diagnostic targets in asthma as PRMT1, PIAS1 and RKIP." (PMID 26911452, 2016). "PIAS1 was specifically and apparently detected in the epithelia of human lobar bronchi, and was significantly more localized in BALF CC10+ cells of patients with allergic asthma than with FBA." (PMID 37393345, 2023).
asthma (2 papers, 2016 to 2023). "Though airway epithelial knock-down of PIAS1 is sufficient to attenuate IL-13-induced airway goblet cell metaplasia, its potential role in allergen-induced mouse model of asthma remains unknown." (PMID 37393345, 2023).
HCMV infection (2 papers, 2024). "Given PIAS1’s role in modulating cytokine signaling-associated gene expression, we examined how it contributes to cytokine-mediated inhibition of HCMV infection." (PMID 38768227, 2024). "Given PIAS1’s described role in inhibiting inflammatory gene expression, and the possibility that it is important to HCMV infection, we performed RNA-seq analysis on control versus PIAS1-targeted cells." (PMID 38768227, 2024). "Collectively, these experiments indicate that PIAS1 limits cytokine-induced anti-viral activities during HCMV infection." (PMID 38768227, 2024). "Collectively, our data indicate that PIAS1 is important for low MOI HCMV infection and that these contributions depend in part on the presence of UL26." (PMID 38768227, 2024). "Our results show that similar to UL26, the cellular PIAS1 protein is critical for limiting anti-viral gene expression during HCMV infection and upon cytokine challenge." (PMID 38768227, 2024). "We find that PIAS1’s anti-inflammatory activity is utilized during HCMV infection to block anti-viral gene expression and support productive infection." (PMID 38768227, 2024). "Taken together, these experiments indicate that inactivation of PIAS1 potentiates anti-viral transcriptional responses resulting in the strong induction of cytokine-signaling genes upon HCMV infection." (PMID 38768227, 2024). "Most importantly, PIAS1 inactivation attenuated WT UL26 HCMV infection, resulting in an antiviral transcriptional environment similar to ΔUL26 infection." (PMID 39687228, 2024). "Inactivation of PIAS1 substantially attenuates WT HCMV infection but has a reduced anti-viral impact on ΔUL26 infection, suggesting that UL26 is necessary for HCMV to benefit from PIAS1’s activity." (PMID 38768227, 2024). "In addition, the inactivation of PIAS1 also resulted in the strong induction of ISG expression during WT HCMV infection, suggesting that PIAS1 is important in limiting ISG expression during normal HCMV infection." (PMID 38768227, 2024). "While each of the different PIAS family members could play important roles during HCMV infection, we focused on PIAS1 as it abundantly accumulated at early times post-infection." (PMID 38768227, 2024). "WT HCMV infection also substantially increased the accumulation of PIAS-type E3-SUMO ligases, including PIAS1, PIAS3, and PIAS4, as well as PIAS2, albeit to a much lesser extent." (PMID 38768227, 2024). "Our results indicate that productive HCMV infection relies on UL26 and PIAS1 to prevent activation of anti-viral gene expression during infection." (PMID 38768227, 2024). "However, upon stimulation by either HCMV infection or TNFα, cytokine signaling genes were strongly induced, partially phenocopying ΔUL26 infection, indicating that the lack of PIAS1 strongly potentiates anti-viral gene expression in the face of an inflammatory challenge." (PMID 38768227, 2024). "However, our results suggest that PIAS1 inactivation did not impact global SUMOylation-induced by HCMV infection, suggesting that HCMV infection induces the activation of other SUMO ligases to drive global increases in SUMOylation." (PMID 38768227, 2024).
lung adenocarcinoma (2 papers, 2019 to 2023). A carcinoma that arises from the lung and is characterized by the presence of malignant glandular epithelial cells. "Therefore, ATAD2 and PIAS1 may be involved in the action mechanism of HPD in lung adenocarcinoma." (PMID 30717818, 2019). "RPL3, HSP90AA1, ATAD2, and PIAS1 as well as USP25, which is targeted by miR-200b, miR-200c, and miR-429, may be the potential targets of HPD in lung adenocarcinoma." (PMID 30717818, 2019). "RPL3, HSP90AA1, ATAD2, as well as PIAS1 and USP25, which is targeted by miR-200b, miR-200c, and miR-429 may show correlations with the sensibilization effect of HPD in lung adenocarcinoma." (PMID 30717818, 2019).
metastatic tumor (2 papers, 2014). "To investigate the role of PIAS1 as a SUMO E3 ligase on metastatic tumor and growth potential in vivo, we determined the effect of expression of the SUMO E3 ligase PIAS1 (CS) mutant in the MDA-MB-231-Luc cells on their ability to form osseous metastases." (PMID 25594015, 2014).
prostate adenocarcinoma (2 papers, 2013 to 2020). "Of relevance for our work, it has been reported elevated expression levels of Ubc9 and PIAS1 enzymes in human prostate adenocarcinoma." (PMID 32209980, 2020).
acute promyelocytic leukemia (1 paper, 2021). An aggressive form of acute myeloid leukemia (AML), characterized by arrest of leukocyte differentiation at the promyelocyte stage, due to a specific chromosomal translocation t(15;17) in myeloid cells. "It is reported that the suppression of PIAS1 abolished the ability of arsenic trioxide, an effective treatment of acute promyelocytic leukemia (APL), to trigger apoptosis in APL cells." (PMID 33759814, 2021).
aortic stenosis (1 paper, 2019). Aortic valve stenosis is a aortic valve disease caused by the incomplete opening of the aortic valve. "Also in PVAT of patients with aortic stenosis, PIAS1 protein levels were found to be expressed at significantly lower levels compared to their epicardial adipose tissue (EAT), and the PIAS1 immunosignal could be localized, among other cells, to adipocytes." (PMID 31906225, 2019).
arteriosclerosis (1 paper, 2019). A vascular disorder characterized by thickening and hardening of the walls of the arteries. "Significantly reduced PIAS1 levels were also observed in PVAT surrounding the aortic root and coronary arteries of patients with coronary artery disease compared to PVAT surrounding the internal mammary artery (IMA), a vessel largely protected from arteriosclerosis." (PMID 31906225, 2019).
bipolar disorder (1 paper, 2024). A disorder of the brain that causes unusual shifts in mood, energy, activity levels and the ability to carry out day-to-day tasks. "Finally, a differential expression of RAD23B and PIAS1 was detected in the ASD, schizophrenia and bipolar disorder datasets." (PMID 39727940, 2024).
cataract (1 paper, 2021). Partial or complete opacity of the crystalline lens of one or both eyes that decreases visual acuity and eventually results in blindness. "In our glucose oxidase (GO) treatment-induced cataract model, we found that GO also regulates PIAS1 expression." (PMID 34195189, 2021).
colorectal cancer (1 paper, 2024). A primary or metastatic malignant neoplasm that affects the colon or rectum. "PIAS1 played a disadvantage prognostic factor in colorectal cancer (DFS)." (PMID 38528630, 2024).
diabetic neuropathy (1 paper, 2021). A chronic, pathological complication associated with diabetes mellitus, where nerve damages are incurred due to diabetic microvascular injury involving small blood vessels that supply these nerves, resulting in peripheral and/or autonomic nerve dysfunction. "In order to further explore the function of PIAS1 in diabetic neuropathy, adenovirus stably overexpressing PIAS1, EZH2, and STAT3 was infected into db/db mice with spontaneous type 2 diabetes mellitus." (PMID 34857740, 2021). "Collectively, PIAS1 can improve diabetic neuropathy by regulating the miR-124-EZH2/STAT3 pathway." (PMID 34857740, 2021). "We speculated that PIAS1 may be a key gene affecting diabetic neuropathy." (PMID 34857740, 2021).
endometrial cancer (1 paper, 2023). Primary or metastatic malignant neoplasm involving the endometrium (mucous membrane that lines the endometrial cavity). "Recently, it has also been demonstrated that miR-182-5p targeted PIAS1 (protein inhibitor of activated STAT) mRNA in endometrial cancer, and the overexpression of PIAS1 inhibited Stat3 activity." (PMID 37887350, 2023).
endothelial dysfunction (1 paper, 2019). In vascular diseases, endothelial dysfunction is a systemic pathological state of the endothelium (the inner lining of blood vessels) and can be broadly defined as an imbalance between vasodilating and vasoconstricting substances produced by (or acting on) the endothelium.
gastric cancer (1 paper, 2020). A primary or metastatic malignant neoplasm involving the stomach. "In addition, other studies have also reported that PIAS1 may function as a tumor suppressor to regulate gastric cancer cell metastasis by targeting the mitogen-activated protein kinase signaling pathway." (PMID 32047143, 2020).
gastric tumors (1 paper, 2017). "Consistent with our findings PIAS1 has been suggested as a useful prognostic biomarker in other epithelial tumors including colon and gastric tumors." (PMID 28493978, 2017).
HIV-1 infection (1 paper, 2015). The type species of lentivirus and the etiologic agent of acquired immunodeficiency syndrome (AIDS). "Transfection of HeLa cells with control siRNA or with siRNA targeting SUMO1, Ubc9 or PIAS1 did not have any effect on HIV-1 infection." (PMID 25880753, 2015).
invasive breast carcinoma (1 paper, 2014). A carcinoma that infiltrates the breast parenchyma. "Furthermore, immunohistochemical data from invasive breast cancers suggested that a positive nuclear signal for the SUMO E2 (Ubc9, UBE2I), and the SUMO E3 protein PIAS1, is associated with good prognostic characteristics." (PMID 25522242, 2014).
large cell neuroendocrine carcinoma of the lung (1 paper, 2025). "The NSCLC with PIAS1-RASGRF1 was a squamous cell carcinoma, while HSPA4-RASGRF2 was identified in a large cell neuroendocrine carcinoma of the lung." (PMID 40615519, 2025).
mastitis (1 paper, 2023). Inflammation of breast tissue during lactation or postpartum due to an obstructed duct or infection. "In this study, the ZRANB3, PIAS1, ACTR3, LPCAT2, MGAT5, and SLC37A2 genes in Xinjiang brown cattle, which are associated with mastitis resistance, were identified using a GWAS." (PMID 37372369, 2023). "Some studies have shown that, among them, the PIAS1 gene is involved in the NF-kB and JAK/STAT signaling pathways, which are closely associated with mastitis." (PMID 37372369, 2023). "Meanwhile, the methylation levels of CpG3, CpG5, CpG8, and CpG15 in the promoter region of the FHIT and PIAS1 genes in the mastitis group were significantly higher than those in the healthy group (p < 0.01), respectively." (PMID 37372369, 2023). "RT-qPCR showed that the expression levels of the FHIT and PIAS1 genes were significantly higher in the healthy group than those in the mastitis group (p < 0.01)." (PMID 37372369, 2023). "These six genes (ZRANB3, PIAS1, ACTR3, LPCAT2, MGAT5, and SLC37A2) are all potentially associated with mastitis resistance." (PMID 37372369, 2023). "Further analysis showed that the methylation levels of the FHIT and PIAS1 genes were higher in the mastitis group than in the healthy group." (PMID 37372369, 2023). "Pyrosequencing analysis showed that the promoter methylation levels of the FHIT and PIAS1 genes in the mastitis group were higher and lower, respectively, than those in the healthy group (65.97 ± 19.82% and 58.00 ± 23.52%)." (PMID 37372369, 2023). "Finally, we consider that the methylation of the FHIT and PIAS1 genes affects the expression of the genes to a certain extent and can be used as an epigenetic marker for mastitis resistance in Xinjiang brown cattle." (PMID 37372369, 2023). "However, in our study, the expression of the PIAS1 gene was down-regulated in the mastitis group, and its expression was significantly positively correlated with the methylation level of the PIAS1 gene promoter." (PMID 37372369, 2023). "However, the methylation level of the PIAS1 gene promoter region in the mastitis group was lower than that in the healthy group (11.48 ± 4.12% and 12.17 ± 4.25%)." (PMID 37372369, 2023). "Changes in the promoter methylation levels of FHIT and PIAS1 may influence the expression of these genes to further regulate the development of mastitis." (PMID 37372369, 2023). "The results of RT-qPCR showed that the FHIT and PIAS1 genes were expressed in the blood of cattle in the healthy and mastitis groups, and the expression levels of both genes were significantly higher in blood from healthy cattle than those with the mastitis group (p < 0.01)." (PMID 37372369, 2023). "Finally, we selected the PIAS1 and FHIT genes and further investigated their effect on mastitis in terms of epigenetics." (PMID 37372369, 2023).
oral cancer (1 paper, 2025). "We found that higher levels of PIAS1 in these surrounding cells were linked to better survival in patients with oral cancer." (PMID 40941002, 2025).
oral squamous cell carcinoma (1 paper, 2025). "This study aimed to characterize the expression and functional relevance of PIAS1 within the TME of oral squamous cell carcinoma (OSCC)." (PMID 40941002, 2025).